HOXD13 (homeobox D13)
Description:
Sequence-specific transcription factor that binds gene promoters and activates their transcription. Part of a developmental regulatory system that provides cells with specific positional identities on the anterior-posterior axis (By similarity).
Synonyms: HOX4I; BDE; BDSD; SPD; SPD1
Tractability: PROTAC: ubiquitination databases record sites on it.
Gene: Protein-coding gene on chromosome 2 (176,092,721 to 176,095,944, forward strand). Ensembl gene ENSG00000128714.
Subcellular location: Nucleus
Subcellular location (Human Protein Atlas): Nucleoplasm
Gene Ontology:
Molecular function: DNA binding; DNA-binding transcription activator activity, RNA polymerase II-specific; sequence-specific double-stranded DNA binding; DNA-binding transcription factor activity; DNA-binding transcription factor activity, RNA polymerase II-specific; RNA polymerase II cis-regulatory region sequence-specific DNA binding; chromatin binding; cis-regulatory region sequence-specific DNA binding
Biological process: positive regulation of transcription by RNA polymerase II; regulation of DNA-templated transcription; regulation of transcription by RNA polymerase II; skeletal system development; embryonic hindgut morphogenesis; prostate gland development; response to testosterone
Cellular component: chromatin; nucleus
Genetic constraint (gnomAD): Loss-of-function variants: 16 observed, 25.4 expected, observed/expected ratio (o/e) 0.63, 90% interval 0.43 to 0.96. The upper end of that interval is the gene's LOEUF score, 0.96, which puts it in group 4 of 6, group 1 being the genes least tolerant of losing a copy. Missense variants: 479 observed, 441.16 expected, observed/expected ratio (o/e) 1.09, 90% interval 1.01 to 1.17. Synonymous variants: 241 observed, 199.8 expected, observed/expected ratio (o/e) 1.21, 90% interval 1.09 to 1.34.
Homologues: Orthologues: macaque HOXD13 (99% identical), chimpanzee HOXD13 (99% identical), pig HOXD13 (96% identical), dog HOXD13 (94% identical), mouse Hoxd13 (93% identical), rat Hoxd13 (93% identical), guinea pig HOXD13 (77% identical), tropical clawed frog hoxd13 (67% identical), rabbit HOXD13 (59% identical). Paralogues in human: HOXA13 (46% identical), HOXC13 (43% identical), HOXB13 (36% identical), HOXA11 (20% identical), HOXC11 (18% identical), HOXD11 (17% identical), HOXB5 (15% identical), HOXB9 (15% identical), HOXC12 (15% identical), HOXD9 (15% identical), HOXA5 (15% identical), HOXA10 (14% identical), and 30 more.
Diseases named in the same sentence as HOXD13 in open-access papers:
HOXD13 is named in the same sentence as 171 diseases in open-access papers, as found by Europe PMC text mining. Sharing a sentence is not in itself a finding about the gene and the disease. The quoted sentences say what the papers report.
breast carcinoma (17 papers, 2011 to 2025). "Another recent report concluded that HOXD13 methylation was a common event in breast cancer and was associated with poor survival in patients." (PMID 28808656, 2017). "Abnormal HOXD13 expression has also been observed in breast cancer, melanoma, cervical cancer, astrocytoma, and pancreatic cancer." (PMID 39744569, 2025). "HOXD10 and HOXD13 gene expressions have been found to be altered in primary breast cancers with respect to normal breast tissue, switching from off to on." (PMID 38907278, 2024). "In breast cancer, the methylation modification and low expression of the HOXD13 promoter are positively correlated with the poor prognosis of breast cancer patients." (PMID 34272834, 2021). "Deregulation of HOXD13 displays a prognostic value in breast cancer." (PMID 31137568, 2019). "HOXD13 is rarely methylated in the sera from breast cancer patient group (13.81%)." (PMID 26918343, 2016). "Moreover we added a new methylated site of HOXD13 in the promoter region, which didn't exist in our previous research, but showed significant methylation in serum from breast cancer patients comparing to benign breast diseases patients and healthy women in this study (P<0.05)." (PMID 26918343, 2016). "Methylation at many gene promoters has been reported to have independent prognostic value in breast cancer including HOXA11, ESR1 and PITX2, HOXD13 CDH22 BRCA1 and RASSF1." (PMID 33461604, 2021). "In summary, the six-marker panel with HOXD13, SFN, RASSF1a, P16, PCDHGB7, and hMLH1 exhibits significantly aberrant methylation in serum cfDNA from breast cancer patients compared with both age-matched healthy women and women with a benign breast disease." (PMID 26918343, 2016). "Accumulating data on these methylation markers including the six genes tested in this study (HOXD13, SFN, RASSF1a, P16, PCDHGB7, and hMLH1) is of interest for further evaluation as serum- or serum-based biomarkers for the detection and monitoring of breast cancer patients." (PMID 26918343, 2016). "In this study, we assessed the promoter methylation of an six-gene panel (SFN, P16, hMLH1, HOXD13, PCDHGB7 and RASSF1a) in serum samples by using MethyLight, to investigate whether it could be used for diagnosis of breast cancer or not." (PMID 26918343, 2016).
synpolydactyly (16 papers, 2007 to 2025). A joint presentation of syndactyly (fusion of digits) and polydactyly (production of supernumerary digits). "In patients with HOXD13 polyalanine tract expansion mutations, synpolydactyly was observed in 155 affected hands and feet and especially in feet (> 35%)." (PMID 34777468, 2021). "The most common amongst these malformations are hand-foot-genital syndrome caused by HOXA13 gene mutation, and synpolydactyly caused by HOXD13 mutation." (PMID 33248450, 2020). "The similar phenomenon has also been reported in previous studies of synpolydactyly, in which some members of the families who carry the HOXD13 mutation showed normal phenotypes in the hands and feet." (PMID 29229001, 2017). "A family was identified in whom expansion of the polyalanine tract in the HOXD13 gene causes autosomal dominant hereditary synpolydactyly." (PMID 25289061, 2014). "Other HOXD13 mutation types have also been associated with synpolydactyly, including nonsense and missense mutations, small deletions, frameshift mutations and splice acceptor mutations." (PMID 25289061, 2014). "In conclusion, the cause of synpolydactyly in the Chinese family examined in the present study was identified to be a polyalanine expansion in the HOXD13 gene." (PMID 25289061, 2014). "The mutations of HOXD13 gene have been involved in synpolydactyly (SPD), and the polyalanine extension mutation of Hoxd13 gene could lead to SPD in mice." (PMID 36804539, 2023). "In contrast to GLI3, similar observational studies of HOXD13 revealed that its disruption was linked to many different digital malformations, including synpolydactyly (SPD1; MIM: 186000), brachydactyly type D (BDD; MIM: 113200), and brachydactyly type E (BDE; MIM: 113300)." (PMID 36035248, 2022). "Most non-syndromic synpolydactyly cosegregates with a mutation in the HOXD13 gene on chromosome 2q31 and is categorized as Synpolydactyly type 1 (SPD1, OMIM 186000), which is also known as syndactyly type II (SD II), according to the nomenclature of Temtamy and McKuisck." (PMID 34777468, 2021). "Mutations in the HOXD13 gene have been previously associated with synpolydactyly." (PMID 25289061, 2014). "For example, in congenital synpolydactyly, HOXD13 mutants with expanded polyalanine form phase-separated condensates that fail to recruit coactivators." (PMID 40507965, 2025). "HOXD13/HOXA13/RUNX2 condensates with expanded polyalanine mutation fail to recruit coactivators and disrupt the formation of transcriptionally active TADs, causing synpolydactyly, hand-foot genital syndrome, or cleidocranial dysplasia." (PMID 40507965, 2025). "However, poly-A repeats in HOXD13, the causative mechanism of a non-neurological condition, synpolydactyly, represents an exception, in which the most likely mechanism leading to increased poly-A tracts are errors in DNA replication." (PMID 29922329, 2018). "While it is known that mutations in HOXA13 or HOXD13 can cause specific limb phenotypes, such as hand-foot-genital-syndrome or synpolydactyly, no HOXA9-related disease phenotype has been identified in patients so far, leaving the role of HOXA9 during human limb development unclear." (PMID 23028966, 2012).
leukemia (13 papers, 2007 to 2024). A malignant (clonal) hematologic disorder, involving hematopoietic stem cells and characterized by the presence of primitive or atypical myeloid or lymphoid cells in the bone marrow and the blood. "In addition, HOXD13 was implicated in neoplastic transformation, resulting in leukemia and different solid tumors." (PMID 28808656, 2017).
acute myeloid leukemia (11 papers, 2012 to 2025). Acute myeloid leukemia (AML) is a group of neoplasms arising from precursor cells committed to the myeloid cell-line differentiation. "HOXD13 is known to contribute to the pathogenesis of acute myeloid leukemia (AML) through the formation of a fusion protein with NUP98." (PMID 39977830, 2025). "The NUP98-HOXD13 (NHD13) fusion gene, which is constructed with nucleoporin 98KDa (NUP98) amino terminus and human homeobox 13 (HOXD13) fusion gene, occurs in MDS or acute nonlymphocytic leukemia patients." (PMID 29228688, 2017).
myelodysplastic syndrome (11 papers, 2012 to 2025). A clonal hematopoietic disorder characterized by dysplasia and ineffective hematopoiesis in one or more of the hematopoietic cell lines. "We used a murine pre-clinical model of myelodysplastic syndrome based on transplantation of cells expressing a NUP98::HOXD13 transgene to investigate 5-Aza-4'-thio-2'-deoxycytidine (Aza TdCyd or ATC), a thiol substituted DNMTi, as a potential therapy." (PMID 38168433, 2023).
glioma (10 papers, 2020 to 2025). A benign or malignant brain and spinal cord tumor that arises from glial cells (astrocytes, oligodendrocytes, ependymal cells). "ChIP analysis of randomly selected genes (HOXA4, HOXA‐AS2, and HOXD13) confirmed the marked H3K27me3 loss associated with H3K4me3 and H3K9ac enrichment in seven IDHwt glioma samples from our cohort." (PMID 33720519, 2021). "Clinical data analysis from the TCGA database showed that a high level of HOXD13 was closely associated with glioma grade and a low survival rate in glioma patients." (PMID 33162825, 2020). "The results of Kaplan-Meier analysis using TCGA dataset showed that a high expression level of HOXD13 was closely associated with a lower survival rate in glioma patients." (PMID 33162825, 2020). "Our experiments suggest that this association may be a functional result of HOXD13 in stimulating glioma cell stemness, invasion, and growth." (PMID 33162825, 2020). "As a target of miR-7156-3p, HOXD13 regulates stem cell proliferation and glioma cell aggressiveness." (PMID 39744569, 2025). "PAX6, BCL6, HOXD13, and FOX2 have also been shown to be associated with glioma in previous studies 48-50." (PMID 33537074, 2021). "In accord with this result, our clinical cohort also showed that HOXD13 expression was positively correlated with glioma grade." (PMID 33162825, 2020). "In conclusion, our study determines that miR-7156-3p acts as a tumor suppressor in glioma by targeting HOXD13." (PMID 33162825, 2020). "Taken together, our findings indicate that HOXD13 is a target of miR-7156-3p in glioma and that miR-7156-3p suppresses HOXD13 expression by directly binding to its 3'-UTR." (PMID 33162825, 2020). "Next, we used the TCGA dataset to investigate the correlations between miR-7156-3p expression levels and HOXD13 or PERP expression levels in glioma." (PMID 33162825, 2020). "Our data showed that overexpression of miR-7156-3p induced anti-tumor effects that were significantly attenuated by HOXD13 overexpression in glioma cells, including tumor cell stemness, invasion, growth, and apoptosis." (PMID 33162825, 2020). "Additional in vitro and animal experiments demonstrated that miR-7156-3p regulates glioma cell stemness, invasion, and growth by mediating HOXD13." (PMID 33162825, 2020). "In this work, we identify and validate that HOXD13 is the predominant target of miR-7156-3p in glioma by using a series of experiments." (PMID 33162825, 2020). "Our transcriptome analysis, qRT-PCR, and Western blotting analysis show that miR-7156-3p negatively regulates HOXD13 expression at both the mRNA and protein levels in glioma cells." (PMID 33162825, 2020). "Our data showed that overexpression of miR-7156-3p significantly inhibited HOXD13 expression, while inhibition of miR-7156-3p increased HOXD13 expression in glioma cells both at the mRNA and protein levels." (PMID 33162825, 2020). "To further investigate the role of HOXD13 in glioma, we performed mRNA sequencing using glioma specimens with high or low HOXD13 expression." (PMID 33162825, 2020). "Similarly, HOXD13 was overexpressed in GBM compared to WHO Grade 3 glioma (confirmed by TCGA and CGGA), LGG (confirmed by TCGA, CGGA, Rembrandt, and qPCR), and normal brain tissue (confirmed by Rembrandt and qPCR)." (PMID 39977830, 2025). "The gene HOXD13 has also been implicated in glioma progression in a ChIP-seq analyses of 14 IDH-mutant gliomas, but this phenotype was not validated in oligodendroglioma." (PMID 39259414, 2024). "miR-7156-3p regulates stemness, invasion, and growth of glioma cells by mediating HOXD13." (PMID 36213580, 2022). "The role of HOXD13 in glioma is an uncharted territory currently." (PMID 33162825, 2020). "Moreover, we unveiled that miR-7156-3p overexpression dramatically suppressed glioma stemness, invasiveness, and tumor growth by downregulating HOXD13." (PMID 33162825, 2020).
glioma (continued). "Upregulated expression of HOXD13 in glioma is previously identified, but the function of HOXD13 in glioma remains unclear." (PMID 33162825, 2020). "Similarly, CCK-8 and invasion assays showed that HOXD13 positively regulated glioma cell growth and invasion." (PMID 33162825, 2020). "Similarly, clinical data from the TCGA database shows that the expression levels of miR-7156-3p and HOXD13 are negatively correlated in glioma." (PMID 33162825, 2020). "Moreover, functional experiments demonstrate that the miR-7156-3p-induced anti-glioma effects are significantly attenuated by overexpression of HOXD13." (PMID 33162825, 2020). "Next, we investigated whether HOXD13 is involved in the anticancer role of miR-7156-3p in glioma." (PMID 33162825, 2020). "Moreover, the mRNA expression level of HOXD13 was closely correlated with glioma grade." (PMID 33162825, 2020). "Therefore, we investigated the function of HOXD13 in glioma." (PMID 33162825, 2020). "The luciferase assay results showed that miR-7156-3p significantly inhibited luciferase activity in glioma cells transfected with the wild-type 3'-UTR of HOXD13 but not in these transfected with the mutant 3'-UTR of HOXD13." (PMID 33162825, 2020). "TCGA dataset analysis showed that the miR-7156-3p expression level was negatively correlated with the HOXD13 expression level in glioma but not with the PERP expression level, suggesting that HOXD13 may be a major target of miR-7156-3p in glioma." (PMID 33162825, 2020).
syndactyly (9 papers, 2007 to 2023). A disease characterized by the presence of syndactyly, including syndromic and non-syndromic forms. "HOXD13 mutations have been linked to two types of human syndactyly including the rare type 2a Vordinborg synpolydactyly (OMIM 186000) and type 5 syndactyly (OMIM 186300)." (PMID 31637260, 2019). "Moreover, 201 Mongolian genome databases and a thousand human genome databases were referenced to further confirm that the pathogenic genetic variant that causes syndactyly in this family is found in HOXD13." (PMID 36195906, 2022). "Point mutations, frameshift mutations, or PAE in the first exon of human HOXD13 can lead to the typical SPD phenotype, and the missense mutations in the second exon led to brachydactyly type E and syndactyly type V." (PMID 37035736, 2023). "Studies have also reported HOXD13 mutations in families with different syndactyly types, e.g., SD1-a, SD1-c, and SD5, which gives a clear indication that HOXD13 has a critical role in limb formation and that it may also interact with other limb-formation genes during the process." (PMID 35627156, 2022). "Hence, the pathogenesis of HOXD13-related syndactyly is through Step III." (PMID 31637260, 2019). "Candidate gene studies on HOXD13, LMBR1, FGF16, BHLHA9, to understand their contribution to both cutaneous and synostosis syndactyly phenotypes, could enhance screening." (PMID 35549993, 2022).
hand-foot-genital syndrome (8 papers, 2007 to 2025). Hand-foot-genital syndrome (HFGS) is a very rare multiple congenital abnormality syndrome characterized by distal limb malformations and urogenital defects. "Several mutations for posterior genes have been described in HoxA13 (Hand-foot-genital syndrome) and HoxD13 (Synpolydactyly)." (PMID 17845724, 2007). "Although the variable phenotypes were observed in the individuals with HOXD13 heterozygous mutations, the defects were only related to limbs, a single organ system, and seldom syndrome although HOXA13 mutations were associated with hand-foot-genital syndrome." (PMID 34777468, 2021). "Similar to HOXD13, HOXA13 might be related to the pathogenesis of both poly-Ala tract expansion-related hand-foot-genital syndrome (HFGS) and some types of cancer, such as thyroid and gastric cancers characterized by the aberrant expression of HOXA13, both at gene and protein levels." (PMID 29186753, 2017).
pancreatic cancer (8 papers, 2019 to 2025). "On the contrary, in pancreatic cancer, HOXD13 displayed on opposite trend being strongly down-regulated in cancer cells." (PMID 34208964, 2021).
prostate carcinoma (8 papers, 2011 to 2025). A carcinoma that arises from epithelial cells of the prostate gland. "In prostate cancer, HOXD13 binds to the SMAD1 promoter, disrupting BMP4-induced EMT and reducing tumor cell invasiveness." (PMID 39744569, 2025). "Both HOXA10 and HOXD13 can promote the occurrence and development of various cancers by increasing the expression of genes and activating signal pathways, nevertheless, both of them can inhibit the expression of genes and suppress the occurrence of prostate cancer." (PMID 36685890, 2022).